BCR (BCR activator of RhoGEF and GTPase)
Diseases named in the same sentence as BCR in open-access papers (continued):
Sharing a sentence is not in itself a finding about the gene and the disease.
lymphoma (continued). "The growing body of evidence shows that lymphoma cells are capable of becoming fully independent of BCR-mediated intracellular signaling and develop alternative cell-activation triggering mechanisms." (PMID 38638855, 2024). "One explanation could be the upregulation of the BcR (B cell Receptor), like in HCV-induced lymphomas." (PMID 33466993, 2021). "Moreover, TGF-β stimulation in MEG-01 cells, which are derived from a CML patient having BCR-ABL fusion protein, and in U937 cells, which are derived from lymphoma, results in suppressed CD48 expression levels and lower susceptibility to NK targeting." (PMID 33602907, 2021). "TCL1A also represses the expression of truncated receptor-type protein tyrosine phosphatase (PTPROt), a phosphatase expressed in naïve B cells that represses lymphoma in Eμ-TCL1A mice, and regulates BCR signals by modulating the activity of tyrosine kinases, including Lyn, Syk and ZAP70." (PMID 34206047, 2021). "Our data indicate that inhibition of GCN5 HAT activity reduces the tumorigenic properties of human Burkitt lymphoma cells by attenuating BCR signaling and that GCN5 may be a viable target for lymphoma drug therapy." (PMID 31645904, 2019). "While persistent BCR-BTK signaling is critical in this and other types of lymphoma, we and others did not see any mutations potentially explaining the reliance of MCL on this signaling pathway." (PMID 31334109, 2019). "Furthermore, only 3 out of 12 mice bearing Eμ-driven BCR-ABL expression succumbed to pre-B and T lymphomas, while 1 out of 3 mice harboring MPSV LTR-driven BCR-ABL expression developed T lymphomas." (PMID 27642303, 2016). "In conclusion, extramedullary T-lymphoblastic blast crisis of CML as a first diagnosis is rare and may be misdiagnosed as lymphoma without BCR/ABL detection by FISH." (PMID 25667640, 2015). "Bone marrow examination ultimately demonstrated T-lymphoblastic leukemia/lymphoma with an abnormal immature T-cell population and isolated ABL1 copy number gain in the absence of BCR::ABL1 fusion." (PMID 42281722, 2026). "As a consequence, the persistence of expanded B cell networks may not simply be regarded as an uncleared and inert BCR-centered “HCV scar,” but as the result of imprinted lymphoma-like BCR signaling maintaining the persistence of these clonal networks." (PMID 39082968, 2024). "The majority of cases of so-called ‘Ph+ lymphoma’ occurred in patients without a diagnosis of CML or acute lymphocytic leukemia (ALL) and it was difficult to state whether the NHL carried the BCR/ABL gene translocation without FISH." (PMID 25667640, 2015).
essential thrombocythemia (49 papers, 2014 to 2026). A chronic myeloproliferative neoplasm that involves primarily the megakaryocytic lineage. "Polycythemia vera (PV), essential thrombocythemia (ET), and primary myelofibrosis (MF) are the most common BCR::ABL1-negative MPNs, though differ in signs, symptoms, hematological and clinical alterations, and genetic findings." (PMID 38654055, 2024). "BCR::ABL1-negative myeloproliferative neoplasms (MPNs) include essential thrombocythemia (ET), polycythemia vera (PV) and primary myelofibrosis (PMF)." (PMID 37002477, 2023). "The somatic mutation JAK2-V617F is frequently observed in BCR/ABL1-negative myeloproliferative neoplasms (MPNs): 92% in polycythemia vera (PV), 55% in essential thrombocythemia (ET), and 50% in primary myelofibrosis (PMF)." (PMID 29928488, 2018). "Genetic testing identified a somatic JAK2 V617F mutation (allelic frequency of 17%), consistent with essential thrombocythemia; no other mutations were detected, including no detectable BCR::ABL1 gene." (PMID 41552126, 2025). "Unlike mutant N-Ras-mediated Socs2 downregulation, several hematopoietic malignancies driven by other oncogenic mutations demonstrate upregulated SOCS2 expression, such as JAK2V617F-positive essential thrombocythemia (ET), BCR/ABL-positive CMLs and FLT3-ITD AMLs." (PMID 35352806, 2022). "While the BCR-ABL fusion protein is the transforming agent in CML, driver mutations in JAK2, CALR, and MPL genes are variably present and are mostly mutually exclusive in Ph−MPNs, which include essential thrombocythemia (ET), polycythemia vera (PV), and primary myelofibrosis (MF)." (PMID 31963765, 2020). "The classic BCR::ABL1-negative MPNs, polycythemia vera (PV), essential thrombocythemia (ET), and primary myelofibrosis (PMF), share an overactive JAK2-signaling as a common characteristic with the key driver genes JAK2, CALR, and MPL." (PMID 38835969, 2024). "This chapter focuses primarily on the classical BCR::ABL1-negative MPN, namely polycythaemia vera (PV), essential thrombocythemia (ET), and primary myelofibrosis (PMF)." (PMID 38835971, 2024). "It is crucial to pursue workup for patients with isolated thrombocytosis through testing for the presence of the BCR-ABL fusion gene or the Philadephia chromosome in both PB and the BM in order to distinguish CML from essential thrombocythemia." (PMID 32528789, 2020). "The classic BCR/ABL‐negative MPNs include polycythaemia vera (PV), essential thrombocythaemia (ET) and primary myelofibrosis (PMF)." (PMID 28677265, 2017). "Myeloproliferative neoplasms, namely the BCR::ABL1-negative subtypes such as polycythemia vera (PV), essential thrombocythemia (ET), and primary myelofibrosis (PMF), are identified as clonal hematopoietic stem cell conditions marked by the aberrant proliferation of myeloid lineages." (PMID 41239536, 2025). "A somatic mutation of JAK2, coding for constitutively activated Jak2-V617F, is frequently observed in BCR/ABL1-negative myeloproliferative neoplasms (MPNs): 96% in polycythemia vera (PV), 55% in essential thrombocythemia (ET), and 65% in primary myelofibrosis (PMF)." (PMID 24404189, 2014). "Primary myelofibrosis (PMF) is a subtype of BCR::ABL1-negative classic MPN, which also includes polycythemia vera (PV) and essential thrombocythemia (ET)." (PMID 38339265, 2024). "The World Health Organization (WHO) defines essential thrombocythemia (ET), polycythemia vera (PV) and primary myelofibrosis (PMF) as classical BCR/ABL-negative MPNs." (PMID 36431092, 2022). "BCR::ABL1-negative MPNs include three major subgroups: polycythemia vera (PV), essential thrombocythemia (ET), and primary myelofibrosis (PMF)." (PMID 36611899, 2022). "Essential thrombocythaemia (ET) is a clonal MPN characterized by excess production of platelets and mature hyperlobulated megakaryocytes, with the presence of mutations in JAK2, CALR, or MPL and the absence of BCR-ABL." (PMID 34778087, 2021).
essential thrombocythemia (continued). "There are mainly two categories based on presence of Ph chromose: Ph (BCR-ABL)-positive CML and Ph-negative group including essential thrombocythemia (ET), polycythemia vera (PCV), and primary myelofibrosis (PMF)." (PMID 34372899, 2021). "As a result, there is an emerging consensus that rather than being separate conditions, the three main types of BCR-ABl negative MPN, Essential Thrombocythaemia (ET), Polycythaemia Vera (PV) and Primary Myelofibrosis (PMF) are stages on a continuum of disease progression." (PMID 27143038, 2016). "Among three traditional BCR::ABL negative MPN entities, polycythemia vera (PV), essential thrombocythemia (ET), and primary myelofibrosis (PMF), PMF exerts the highest tendency for progression and death." (PMID 40217782, 2025).
chronic lymphocytic leukemia (38 papers, 2014 to 2026). "IGLV3-21R110 is a point mutation enabling autonomous B-cell receptor (BCR) signaling in chronic lymphocytic leukemia (CLL)." (PMID 42306064, 2026). "Cell-autonomous B-cell receptor (BcR)-mediated signalling is a hallmark feature of the neoplastic B lymphocytes in chronic lymphocytic leukaemia (CLL)." (PMID 28598442, 2017). "In our previous studies, both cell-surface and serum FcμR levels were elevated in patients with chronic lymphocytic leukemia (CLL), where antigen-independent self-ligation of BCR is a hallmark of the neoplastic B cells." (PMID 35784336, 2022). "The engagement of the B cell receptor (BcR) on the surface of leukemic cells represents a key event in chronic lymphocytic leukemia (CLL) since it can lead to the maintenance and expansion of the neoplastic clone." (PMID 36430731, 2022). "Although typically regarded as a T-cell specific tyrosine kinase, LCK is an important mediator of BCR signaling in B-cell chronic lymphocyte leukemia (B-CLL) and found at significant levels in CD5+ B1 cells." (PMID 34113352, 2021). "Key processes in the onset and evolution of chronic lymphocytic leukemia (CLL) are thought to include chronic (antigenic) activation of mature B cells through the B cell receptor (BcR), signals from the microenvironment, and acquisition of genetic alterations." (PMID 34513715, 2021). "B cell receptor Immunoglobulin (BcR IG) repertoire of Chronic Lymphocytic Leukemia (CLL) is characterized by the expression of quasi-identical BcR IG." (PMID 32156260, 2020). "Treatment of chronic lymphocytic leukemia has advanced substantially as our understanding of the kinase signal transduction pathways driven by the B cell receptor (BcR) has developed." (PMID 32664705, 2020). "The current work aims to categorize chronic lymphocytic leukemia (CLL) patients based on their 3-dimensional protein structures of the clonotypic B cell receptor immunoglobulin (BcR IG) amino acid (IG) sequences following on the shape-based approach." (PMID 30453883, 2018). "Chronic lymphocytic leukaemia (CLL) is characterized by cell-autonomous B-cell receptor (BcR)-mediated signalling of neoplastic B lymphocytes." (PMID 28598442, 2017). "Several lines of evidence indirectly suggest that antigenic stimulation through the B‐cell receptor (BCR) supports chronic lymphocytic leukemia (CLL) development." (PMID 28899929, 2017). "The SLAMF1 receptor was reported to be an important modulator of the BCR (B cell receptor) signaling axis and may improve immune control in chronic lymphocytic leukemia by interfering with NK cells." (PMID 34461858, 2021). "Finally, an intron variant of ZAP70 (rs7425883) is associated with a decreased risk of developing non-Hodgkin lymphoma, and aberrant elevated expression of ZAP70 in B cell CLL cells correlates with enhanced BCR signaling in the leukemic cells and poorer prognosis." (PMID 34012443, 2021). "BCR signaling pathway inhibitors such as ibrutinib, idelalisib, and fostamatinib (respective inhibitors of Bruton’s tyrosine kinase, PI3Kδ, and spleen tyrosine kinase) represent a significant therapeutic advance in B cell malignancies, including chronic lymphocytic leukemia (CLL)." (PMID 25632006, 2015). "Previously, we have shown that chronic lymphocytic leukemia (CLL), an indolent subtype of lymphoma, can be detected over 16 years prior to clinical diagnosis by sequencing the B-cell receptor immunoglobulin (BCR IG) gene repertoire in the peripheral blood." (PMID 37035202, 2023). "In chronic lymphocytic leukemia (CLL), BTK is upregulated, contributing to a continuously activated BCR signaling pathway." (PMID 37771591, 2023). "Cross‐linking of the B‐cell receptor (BCR) induces transcriptional activation of immediate early genes (IEGs) including EGR1 and DUSP2 in chronic lymphocytic leukaemia (CLL)." (PMID 32306542, 2020).
chronic lymphocytic leukemia (continued). "The success stories with targeted therapies directed against PML::RARA and BCR::ABL in acute promyelocytic and chronic lymphocytic leukemia, respectively, but also the more recent clinical experience with inhibitors of kinase fusion proteins found in sarcoma, underscore this notion." (PMID 38611033, 2024). "High CCL4 protein level was also found in chronic lymphocytic leukemia B cells co‐cultures with nurse‐like cells, and the induction of CCL4 was abolished by a Syk inhibitor (R406), suggesting that nurse‐like cells induce the chemokine via B‐cell receptor (BCR) activation." (PMID 41208700, 2025). "The ontogeny and evolution of chronic lymphocytic leukemia (CLL) are critically dependent on interactions between leukemic cells and their microenvironment, including antigens, the latter recognized through the clonotypic B-cell receptor immunoglobulin (BcR IG)." (PMID 34804974, 2021).
acute leukemia (27 papers, 2012 to 2025). A clonal (malignant) hematopoietic disorder with an acute onset, affecting the bone marrow and the peripheral blood. "Notably, the number of mutations associated with BCR::ABL1-negative MPNs is smaller than those of acute leukemias and solid tumors, and the genetic mutation analyses play a significant role in confirming diagnosis and prognosis." (PMID 37629188, 2023). "However, the identification of the BCR::ABL1 fusion (considered the hallmark of CML) as the primary oncogenic event through the clonal ontogeny of these cases of acute leukemia raises several concerns." (PMID 37895120, 2023). "This study focuses on Philadelphia chromosome-positive acute leukemia patients, examining the correlation between BCR::ABL1 transcript levels (PCR-MRD) and a standardized flow cytometry-based MRD detection method (FCM-MRD) in B-ALL." (PMID 40076750, 2025). "This is a rare phenomenon and is distinct from the blastic transformation of CML and mixed phenotype acute leukemia (MPAL) with BCR::ABL1 fusion." (PMID 38633128, 2024). "Subsequently, after undergoing acute leukemia therapy, both BCR/ABL1 (IS) levels and the proportion of CD56briCD38+ neutrophils dropped below the designated threshold values." (PMID 39559206, 2024). "The current studies demonstrate that most pediatric patients achieve complete cytogenetic remission and a BCR::ABL1 transcript level below 1% after acute leukemia induction chemotherapy with added TKI treatment." (PMID 36707619, 2023). "Regarding acute leukemias, the BCR::ABL1 rearrangement can, therefore, be detected in AML arising from BC-CML, in de novo AML, and throughout the course of AML, as a secondary event." (PMID 37895120, 2023). "This is the well known benchmark dataset on the ABL/BCR chimera in acute leukemia patients ALL (ALL Bioconductor package)." (PMID 31652275, 2019). "An emerging body of evidence suggests a central role for PP2A in Ph+ acute leukemia, whereas BCR-ABL and related signaling molecules are both substrates of PP2A." (PMID 28445932, 2017). "In conclusion, our results showed CFTR was highly expressed in Ph+ acute leukemia, which protected and maintained the continuous activation of BCR-ABL and the canonical Wnt/β-catenin signaling pathway by decreasing PP2A phosphatase activity." (PMID 28445932, 2017). "Third, CML diagnosis was based on the institutional diagnosis, and the diagnosis was not centrally reviewed, which could lead to unclear discrimination between BP-CML and acute leukemia with BCR::ABL1." (PMID 40088374, 2025). "We were able to directly cross-check the clinically most relevant RTK mutations in acute leukemia (i.e. FLT3-ITD, KIT D816V/Y, BCR/ABL1) transfected into an isogenic Ba/F3 background against a panel of leukemic cell lines harboring a corresponding RTK mutation." (PMID 23497317, 2013). "Measurable residual disease in Philadelphia chromosome-positive disease, achieved with the BCR::ABL1 quantitative method, is the standard of care in CML and Ph+ acute leukemias." (PMID 40076750, 2025). "Until the diagnosis is confirmed by the detection of BCR::ABL1 and the definition of the immunophenotype (lymphoid vs. myeloid), supportive therapy is administered as in acute leukemia (prevention of tumor lysis syndrome according to institutional standards)." (PMID 36707619, 2023). "The response to therapy should be assessed in the same way as in acute leukemia, following the standards of the respective protocol for morphology, cytogenetics, flow cytometry, and molecular MRD markers including BCR::ABL 1 transcripts by real-time PCR and IgH/TCR markers." (PMID 36707619, 2023). "Finally, high CFTR expression inhibits the phosphatase activity of PP2A to protect and maintain the continuous activation of BCR-ABL and canonical Wnt/β-catenin signaling via the interaction with the PP2AA subunit in the cytosol of Ph+ acute leukemia cells." (PMID 28445932, 2017).
acute leukemia (continued). "HP-β-CyD significantly inhibited the growth of mouse Pro-B cell Ba/F3 cells expressing wild-type BCR-ABL (hereafter Ba/F3 BCR-ABLWT), and BV173 cells derived from a human Philadelphia chromosome-positive (Ph+) acute leukemia patient, in a dose- and time-dependent manner." (PMID 26535909, 2015). "In our study, we found that p-BCR-ABL and classical Wnt/β-catenin signaling were significantly down-regulated (i.e., Dvl-2 and β-catenin were significantly down-regulated and p-GSK3β was significantly up-regulated) when CFTR protein was reduced by CFTRinh-172 and shRNA in Ph+ acute leukemia cells." (PMID 28445932, 2017). "Therefore, we can assume that the likelihood of physical contact between TEL and AML1 (BCR and ABL) gene territories in a fraction of HSPC (which represents subpopulations of progenitors, HSC/MPP, HSC and MPP) of Patient 4 was increased and might contribute to the development of acute leukemia." (PMID 40089517, 2025).
polycythemia vera (27 papers, 2013 to 2025). "While CML and BCR::ABL1-negative MPN have been considered to be mutually exclusive, the WHO classification requires the exclusion of the BCR::ABL1 fusion in all cases of suspected MPN that cannot be clinically classified as Polycythemia vera." (PMID 40906032, 2025). "The classic BCR/ABL-negative MPNs include polycythemia vera (PV), essential thrombocythaemia (ET) and primary myelofibrosis (PMF)." (PMID 26275051, 2015). "Although BCR-ABL has robust transformation potential, JAK2 V617F-positive polycythemia vera (PV) is characterized by a long and stable latent phase." (PMID 32272770, 2020).